IL6 (interleukin 6)
Diseases named in the same sentence as IL6 in open-access papers (continued):
Sharing a sentence is not in itself a finding about the gene and the disease.
asthma (continued). "JQ1/SGCBD01 and I-BET762 inhibited FCS+TGF-β-induced ASM cell proliferation and IL-6 and CXCL8 release in healthy individuals (≥ 30 nm) and in nonsevere and severe asthma patients (≥100 nm), with the latter requiring higher concentrations of these mimics." (PMID 25697361, 2015). "Our chromatin immunoprecipitation data show that there was a greater amount of enrichment of Brd4 at the IL6 and IL8 promoters at baseline in ASM cells from severe asthma compared with nonasthmatics subjects." (PMID 25697361, 2015). "IL-6 and 8-isoprostane, as well as substance P and neurokinin A, in induced sputum seem to predict the presence of GER in subjects both with or without asthma." (PMID 23653634, 2013). "We found that STAT3 phosphorylation as well as the expression of IL-6 and IL-17A could not be reversed by Dex treatment, which indicates their involvement in corticosteroid resistance of OVA- and ozone-induced asthma." (PMID 34760922, 2021). "The serum OX40L level showed a significant positive correlation with serum IgE, blood percentages of eosinophils and neutrophils, serum IL-6 and TSLP, and showed a negative correlation with asthma control test (ACT) score and forced expiratory volume in first second (FEV1%)." (PMID 30890137, 2019). "We observed comparatively similar levels of acute inflammatory markers (e.g., – IL-1β, IL-6, TNFα) in TRPM-stimulated whole blood from children with and without asthma, which was contrary to our a priori study hypothesis." (PMID 28424616, 2017). "This is consistent with our finding that pDC depletion produced significantly lower IL-6 and IFN-α, and somewhat lower TNF-α, consistent with the notion that pDC function might be impaired in asthma." (PMID 29118754, 2017). "The results suggest that targeting p38 MAPK may reduce IL-6 but not other important chemokines such as MCP-1/CCL2, and that targeting STAT signaling may reduce MCP-1/CCL2 in airway smooth muscle in asthma." (PMID 25849622, 2015). "Conversely, IL-6 and 8-isoprostane were elevated in GER patients, irrespective of asthma status." (PMID 23653634, 2013). "Dex could not reduce the levels of IL6, and IL8 in the macrophages of severe asthma patients." (PMID 37208441, 2023). "Temperature change could also affect the concentrations of inflammatory markers, such as C-reactive protein, fibrinogen, and interleukin-6 (IL-6), which induces non-infectious respiratory diseases (NIRD), such as asthma and chronic obstructive pulmonary disease (COPD)." (PMID 34063510, 2021). "While modest evidence of correlation exists for cytokines such at TNF-α, IL-1β, and IL-6, there is a notable lack of correlation evident for the IL-8 responses to endotoxin and TRPM, whether the study subjects were considered as a single group, or as sub-groups based on asthma control status." (PMID 28424616, 2017).
autoimmune disease (787 papers, 2008 to 2026). A disorder resulting from loss of function or tissue destruction of an organ or multiple organs, arising from humoral or cellular immune responses of the individual to their own tissue constituents. "Interleukin-6 (IL-6) is a key immunomodulatory cytokine implicated in diverse physiological processes and pathological conditions, including autoimmune diseases, cancers, and cytokine storms." (PMID 42281397, 2026). "Persistent dysregulation of IL-6 is linked not only with autoimmune diseases but also in some cancers since elevated IL-6 levels are involved in inflammation-driven tumors." (PMID 40066438, 2025). "Interleukin 6 (IL-6) is a cytokine involved in different biological events associated with inflammatory processes, autoimmune diseases, and lymphoproliferative disorders." (PMID 39857029, 2025). "The chemokine IL-6 is mainly derived from vascular endothelial cells, monocyte macrophages, fibroblasts, etc., and the chronic overproduction of IL-6 is associated with autoimmune diseases, chronic inflammatory conditions, and cancers." (PMID 40784044, 2025). "While epidemiological and animal data remain promising, prenatal infection, autoimmune disease, or elevated maternal cytokines (especially IL-6 and IL-17a) increase offspring ASD risk." (PMID 41008370, 2025). "The MAG1-induced increase in IL-6 represents an additional risk factor for autoimmune diseases associated with molecular mimicry." (PMID 41041334, 2025). "Currently, IL-6/IL-6R pathway inhibitors, such as tocilizumab, are predominantly utilised for their anti-inflammatory effects in autoimmune diseases, cytokine release syndrome, cancer-associated cachexia, and to enhance tolerance to immunotherapy." (PMID 39858048, 2025). "Although IL-6 helps the body fight, chronic release causes inflammation-associated disease and even autoimmune disease." (PMID 39916822, 2025). "IL-6 is produced mainly by myeloid cells, and its dysregulation is linked to autoimmune diseases like RA." (PMID 40066438, 2025). "IL‐6 is an important inflammatory cytokine that promotes an acute phase response to infections and has been implicated in the pathogenesis of multiple autoimmune diseases including ARF/RHD." (PMID 40642941, 2025). "By stimulating dendritic cells, aldosterone activates CD8+ T cells and polarizes CD4+ T cells to Th17, a phenotype associated with inflammation and autoimmune disease, secondary to the production of interleukin-6 (IL-6) and tumor necrosis factor-α (TNF-α)." (PMID 40426991, 2025). "IL-6 is also implicated in several autoimmune diseases, and anti-IL-6 inhibitors, such as tocilizumab, are currently used to treat RA and are being tested in other autoimmune diseases." (PMID 41041334, 2025). "Taken together, these results highlight IL-6R as a key regulator of Th17 cell metabolism via metabolic mediators that can be selectively targeted for the treatment of IL-6-associated pathologies such as autoimmune disease and infection-associated inflammation." (PMID 40936905, 2025). "Abnormal levels of IL-6 and its receptor components have been associated with various pathological conditions, including certain blood cancers, autoimmune disorders, and prostate malignancies." (PMID 41283471, 2025). "Th17 cells are involved in the control of bacterial and fungal infections, are associated with autoimmune diseases, and induce the production of proinflammatory cytokines such as IL-6, IL-21, TGF-β, and particularly IL-23." (PMID 41552147, 2025). "It is well established that blood cytokine levels, particularly IL‐6, tend to increase with age and are associated with senescence and the development of autoimmune diseases." (PMID 40037793, 2025). "Interleukin-6 (IL-6) is a pleiotropic proinflammatory cytokine, and its dysregulation is associated with chronic inflammatory and autoimmune diseases." (PMID 39858450, 2025).
autoimmune disease (continued). "The homeostatic role versus the pathogenic role of IL-6 in various autoimmune diseases has been widely debated." (PMID 39062809, 2024). "In line with other autoimmune disorders, elevated NaCl concentrations have been associated with the release of pro-inflammatory cytokines such as IL-1β and IL-6 in MD." (PMID 38742115, 2024). "The levels of another interleukin, IL-6, are closely associated with inflammation and the development of autoimmune diseases, and it has been established to regulate Th 17 cell differentiation." (PMID 39199828, 2024). "Accordingly, administration of IL-6 pathway inhibitors to treat autoimmune diseases was associated with increased body weight and body mass index (BMI) in humans." (PMID 39723211, 2024). "IL-6 is multifunctional and central to regulating immune and inflammatory responses, linked to various autoimmune diseases, including AR, SS, SSc, and SLE." (PMID 38675400, 2024). "Increased production of IL-6 is heavily associated with chronic inflammation and various autoimmune disorders; it acts in localized inflammatory responses by regulating acute-phase pro-inflammatory proteins." (PMID 39684535, 2024). "Since the plasma IL-6 levels have been shown to be associated with autoimmune diseases and infectious diseases, we specifically analyzed the bacteria associated with the IL-6 levels." (PMID 39065221, 2024). "As Th17 is also osteoclastogenic, we would expect increased levels of IL-6 to be associated with an increased fracture risk, even outside of established autoimmune disease." (PMID 38658414, 2024). "Based on our findings, we conclude that long-term reduction in systemic IL-6 levels (e.g. by treating the existing autoimmune disease) is essential to reduce the associated vascular phenotype." (PMID 39015379, 2024). "IL-6, a cytokine secreted by M1 macrophages, contributes to the inflammatory milieu and is implicated in the pathogenesis of various inflammatory and autoimmune diseases." (PMID 39061957, 2024). "The suppression of IL-6/JAK/STAT3 signaling has gained emphasis as a therapeutic target for autoimmune diseases and several cancer types associated with immune response disorders characterized by abnormal secretion of inflammatory cytokines." (PMID 37488213, 2023). "Due to its prominent proinflammatory function, IL-6 is regarded as a key player in the regulation of the immune response, and dysregulation of the IL-6/IL-6R system has already been associated with the pathogenesis of several autoimmune diseases." (PMID 37626843, 2023). "STAT3 is a transcription factor activated by cytokines such as IL-6, IL-10, and growth factors, and is implicated in the activation of Th17 cell responses and autoimmune diseases as well as anti-inflammatory responses." (PMID 36882813, 2023). "There appear to be multiple benefits associated with interfering with the IL-6/STAT3 signaling axis in the treatment of autoimmune diseases." (PMID 38015631, 2023). "Interleukin-6 is a key cytokine in many inflammatory and autoimmune diseases and IL-6, as well as IL-6 signaling, have been implicated in pain pathogenesis." (PMID 35909446, 2022). "Deregulated expression of IL-6 is associated with inflammatory and autoimmune diseases as well as skewed hematopoiesis and leukemia." (PMID 36248849, 2022). "Consistent with this, a unique effect of IDMF in this study was down-regulation of the gene encoding IL-6, which has now emerged as a therapeutic target in multiple autoimmune diseases." (PMID 35455458, 2022). "In CD4+ T cells, loss of Regnase-1 leads to markedly elevated IL-6 levels and, consequently, exacerbated autoimmune disease risk as demonstrated in the experimental autoimmune encephalitis model of multiple sclerosis." (PMID 36294909, 2022). "IL‐6 promotes B cell differentiation and drives immunoglobulin production, and dysregulated IL‐6 production has been implicated in specific autoimmune diseases." (PMID 35060328, 2022).
autoimmune disease (continued). "Overproduction of IL-6 and dysregulation of the IL-6 receptor (IL-6R) have been implicated in the pathogenesis of inflammatory disease, autoimmune disease, and cancer, driving the development of multiple drugs to block the IL-6 signaling pathway." (PMID 36282595, 2022). "In this report, we focus on its function in the production of pro-inflammatory cytokines, including IL-6 and IL-8, which are implicated in several autoimmune diseases and host defense against infection." (PMID 35164164, 2022). "IL-6/IL-6R/gp130 signaling is implicated in the development of inflammatory and autoimmune diseases, including novel coronavirus disease 2019 (COVID-19)." (PMID 35493452, 2022). "The observed inverse association between circulating 25OHD and IL-6, a cytokine involved in inflammatory response and autoimmune diseases, contributes to characterize, at least in part, the possible role exerted by vitamin D in this disease." (PMID 34126960, 2021). "Abnormal production of some cytokines such as tumour necrosis factor (TNF)-α, interleukin-1-beta (IL- 1β), soluble IL-2 receptor (sIL-2R), IL-6, and chemokine IL-8 have been implicated in the pathogenesis of various inflammatory and autoimmune diseases." (PMID 34403420, 2021). "Elevated serum levels of IL-6 have been implicated in autoimmune disease (i.e., RA, SLE) as well as other chronic, inflammatory conditions." (PMID 34681644, 2021). "TNF-α plays a critical role in the pathogenesis of certain autoimmune diseases, and AA is associated with the increase in levels of IL-6." (PMID 34674748, 2021). "IL-6 has also been implicated in a variety of other autoimmune diseases, including autoimmune encephalomyelitis and rheumatoid arthritis." (PMID 34696354, 2021). "In murine models of autoimmune diseases, IL-6 mediates the induction of pathogenic TH17 cells to eventually trigger the onset of disease." (PMID 33375150, 2020). "The results showed that CBP EVs downregulated human IL-2, IFN-γ, and IL-6, which are associated with the differentiation of Th1 and Th17 cells and the development of autoimmune diseases." (PMID 32308765, 2020). "Dysregulated IL-6 production has been implicated in the development of various autoimmune diseases and chronic inflammatory diseases." (PMID 31523783, 2019). "The previous studies have demonstrated that the levels of both IL-21 and IL-6 are significantly associated with the frequency of TFH cells in the autoimmune diseases." (PMID 31875006, 2019). "The same locus has been associated with pediatric autoimmune diseases, although correlation between the variant increasing IL-6 and the autoimmune disease risk variant is poor (r2 = 0.055)." (PMID 30332657, 2018). "Macrophages from Regnase-1 knockout mice produce increased levels of IL-6 and the mice have been shown to spontaneously develop autoimmune diseases, indicating that post-transcriptional regulation of IL-6 is critically linked to IL-6 production." (PMID 30423923, 2018). "In patients with various underlying medical conditions, ranging from autoimmune disease to cardiac disease, use of statins resulted in decreased IL6, IL10, IP10, MMP2 and MMP610–12." (PMID 30464247, 2018). "Especially the SNP 174 G < C (rs1800795) in the IL-6 promoter region affects the transcription and secretion of IL-6 and has been associated with several autoimmune disorders." (PMID 28642760, 2017). "The present study was designed to address the extent to which IL6 contributes to the autoimmune disease caused by Yaa in BXSB mice and its cellular sources." (PMID 27050763, 2016). "IL-6 levels rise in lacrimal and ocular surface tissues in patients with Sjögren syndrome (an autoimmune disorder and an important cause of dry eye)." (PMID 27047687, 2016). "Interleukin 6 (IL-6) is a cytokine that plays an important role in immune response and is implicated in the pathogenesis of many diseases, such as autoimmune diseases, multiple myeloma and prostate cancer." (PMID 26664467, 2015).
autoimmune disease (continued). "TLR4 signalling up-regulates IL-6, and aberrant expression of both of these genes has been implicated in some autoimmune diseases." (PMID 24944008, 2015). "The rs1800795 gene polymorphism of IL-6 is associated with various autoimmune diseases, like multiple sclerosis." (PMID 26640809, 2015). "Th17 cells, CD4+ T cells that secrete IL-17, are pathogenic in autoimmune diseases, and their differentiation and expansion are driven by the cytokines IL-6 and TGF-β." (PMID 26071315, 2015). "Further evidence provided by genetic studies showed that IL-6-deficient mice are resistant to the development of autoimmune diseases such as myocarditis and EAMG." (PMID 25627031, 2015). "Interleukin-6 (IL-6) is a critical regulator of the immune system and has been widely implicated in autoimmune disease." (PMID 24670876, 2014). "Autoimmune disease susceptibility in women, such as multiple sclerosis, has been related with the influence of IL6 which plays a key role in autoimmune diseases, since it is a T cell differentiation switch factor for Tregs and Th17 cells." (PMID 24498974, 2014). "Dysregulated production of IL6 and its receptor are implicated in the pathogenesis of many diseases, including multiple myeloma, autoimmune diseases, and prostate cancer." (PMID 25340798, 2014). "From all polymorphisms within the IL-6 gene, the promoter polymorphism −174G/C seems to be of greatest significance for the development of autoimmune diseases." (PMID 24106699, 2013). "In support of these observations, IL-6 deficiency suppressed the development of autoimmune diseases in mice, and treatments with anti-IL-6 or anti-IL-6 receptor antibodies have cured these disorders in some cases." (PMID 23874602, 2013). "Given the increased susceptibility of women to MS and the significance of IL6 in the autoimmune process compared to IFNγ, it is logical to assume that IL6 pathways are in some way implicated in the prevalence of autoimmune diseases in women." (PMID 23148845, 2012). "Since women are more susceptible to MS disease and the IL6 has a more significant role in the autoimmune process compared to IFNγ, it is logical to assume that IL6 pathways are in some way implicated in the prevalence of autoimmune diseases in women." (PMID 23148571, 2012). "TCD4+ cells that secrete IL-17, Th17 cells, are pathogenic in autoimmune diseases, and their development and expansion is driven by the cytokines IL-6, TGF-beta, IL-21, IL-1, and IL-23." (PMID 22400033, 2012). "Like other autoimmune diseases, Th17 cells and their effector cytokines (such as interleukin 6) have been implicated in pathogenesis." (PMID 23202933, 2012). "Excessive IL-6 production is implicated in autoimmune diseases and metabolic inflammation, suggesting that its modulation could mitigate systemic inflammatory responses and prevent long-term tissue damage." (PMID 41304898, 2025). "The proinflammatory cytokines IL-23, TNF-α, and IL-6, induced by S. copri-OMVs in monocyte-derived macrophages, are related to the generation of IL-17-secreting Th17 cells and a shift in the Th17/Treg balance—a hallmark of autoimmune diseases such as RA." (PMID 40332148, 2025). "Importantly, IL6 signaling through its receptor (IL6R) was associated with sex stratification as a risk factor for several autoimmune diseases." (PMID 39406500, 2024). "The hypothesis of the involvement of HCN channels in the electrophysiological abnormalities induced by cardiac cytokines stemmed from the evidence of the association between increased IL6 levels occurring in inflammatory and autoimmune diseases." (PMID 39596280, 2024). "HUVECs stimulated with these antibodies displayed a significantly elevated production of IL-6, which is heavily associated with chronic inflammation and various autoimmune disorders due to its modulatory effect on the production of acute phase pro-inflammatory proteins." (PMID 39684535, 2024).